HFM1 (helicase for meiosis 1)
Description:
Required for crossover formation and complete synapsis of homologous chromosomes during meiosis.
Synonyms: MER3; FLJ39011; FLJ36760; POF9; SEC63D1; Si-11; Si-11-6; helicase
Tractability: PROTAC: ubiquitination databases record sites on it.
Gene: Protein-coding gene on chromosome 1 (91,260,766 to 91,404,856, reverse strand). Ensembl gene ENSG00000162669.
Subcellular location (Human Protein Atlas): Golgi apparatus; Vesicles
Gene Ontology:
Molecular function: 3'-5' DNA helicase activity; ATP hydrolysis activity; DNA helicase activity; ATP binding; nucleic acid binding
Biological process: resolution of meiotic recombination intermediates
Cellular component: Golgi apparatus; nucleus
Genetic constraint (gnomAD): Loss-of-function variants: 25 observed, 32.91 expected, observed/expected ratio (o/e) 0.76, 90% interval 0.55 to 1.06. The upper end of that interval is the gene's LOEUF score, 1.06, which puts it in group 4 of 6, group 1 being the genes least tolerant of losing a copy. Missense variants: 313 observed, 346.4 expected, observed/expected ratio (o/e) 0.9, 90% interval 0.82 to 0.99. Synonymous variants: 108 observed, 113.48 expected, observed/expected ratio (o/e) 0.95, 90% interval 0.81 to 1.12.
Homologues: Orthologues: chimpanzee HFM1 (99% identical), macaque HFM1 (96% identical), dog HFM1 (86% identical), pig HFM1 (82% identical), rabbit HFM1 (81% identical), guinea pig HFM1 (79% identical), mouse Hfm1 (77% identical), rat Hfm1 (76% identical), tropical clawed frog hfm1 (55% identical), zebrafish hfm1 (42% identical). Paralogues in human: ASCC3 (25% identical), SNRNP200 (24% identical), POLQ (14% identical), HELQ (13% identical), DDX60 (12% identical), DDX60L (11% identical), SKIC2 (11% identical), MTREX (10% identical).
Diseases named in the same sentence as HFM1 in open-access papers:
HFM1 is named in the same sentence as 20 diseases in open-access papers, as found by Europe PMC text mining. Sharing a sentence is not in itself a finding about the gene and the disease. The quoted sentences say what the papers report.
Infertility (5 papers, 2013 to 2024). "Like our findings in Hfm1-KO mice, the mutations in Fus led to infertility in heterozygous male mice with increased numbers of mismatched chromosomes and abnormal synapsis in spermatocytes." (PMID 38822414, 2024). "HFM1 P/LP variants have been reported in several women with infertility and POI under both the dominant and the recessive modes, of which one had an HM, and in infertile men under the recessive mode." (PMID 39545410, 2024). "Studies have demonstrated that Hfm1 mutations affect the mid- to late-stages of HR, impairing folliculogenesis and causing infertility by reducing crossovers and failing to synapsis." (PMID 37430352, 2023). "Mice with Hfm1 mutations exhibit reduced follicular reserve and reduced egg quality leading to infertility or subfertility." (PMID 37430352, 2023). "Hfm1/mer3 mutants display severe deficiencies in chiasma formation, high levels of chromosome missegregation at meiosis I and partial or total infertility." (PMID 23555294, 2013). "Therefore, we believed that HFM1 deletion could lead to a defect in the first meiosis in mice, thus causing an increase in oocyte apoptosis and the inability to establish a normal primordial follicle pool, leading to POI or even infertility." (PMID 38822414, 2024).
Azoospermia (4 papers, 2020 to 2024). Absence of any measurable level of sperm,whereby spermatozoa cannot be observed even after centrifugation of the semen pellet. "HFM1 is essential for mammalian fertility as mutated HFM1 was found in human patients with azoospermia or POI syndromes and removing HFM1 causes a drastic reduction of COs and partially affects synapsis in mice." (PMID 36910159, 2023). "Correspondingly, direct sequencing of the coding regions in HFM1 gene proved that HFM1 gene variants may associate with idiopathic oligo/azoospermia in Chinese men8." (PMID 32606310, 2020). "And recent studies showed the mutations in the HFM1 gene were associated with the occurrence of POI in women and oligospermia/ azoospermia in men." (PMID 38822414, 2024). "A knockout (Hfm1-KO) mouse model used in a study found that Hfm1−/− mice showed testicular hypoplasia and azoospermia in male mice, and had smaller ovaries and reduced numbers of follicle and corpus in female mice." (PMID 38822414, 2024).
premature ovarian failure (3 papers, 2020). "HFM1 is a candidate gene of premature ovarian failure (POF), hence it is also known as POF9." (PMID 32606310, 2020).
Premature ovarian insufficiency (2 papers, 2019 to 2024). Amenorrhea due to loss of ovarian function before the age of 40. "In our study, the novel heterozygous splice-altering mutation in HFM1(c.3470G > A) may be a cause of premature ovarian insufficiency and further exploration can be made to explain the in-depth pathogenesis." (PMID 31279343, 2019). "Helicase for meiosis 1 (HFM1), a putative DNA helicase expressed in germ-line cells, has been reported to be closely associated with premature ovarian insufficiency (POI)." (PMID 38822414, 2024).
amenorrhea (1 paper, 2023). The absence of menses in a woman who has achieved reproductive age. "The other 11 genes were not linked to a specific type of amenorrhea, including mutations in three genes (HFM1, MSH4 and POLG) previously reported in SA and eight genes described in both PA and SA." (PMID 36732629, 2023).
brain cancer (1 paper, 2025). A primary or metastatic malignant neoplasm affecting the brain. "A notable example of this phenomenon, observed only in the paediatric brain cancer cohort (PBCA-DE) was in the HFM1 gene (Helicase for Meiosis 1)." (PMID 41345172, 2025). "In our results, the role of epigenetics is further highlighted by the 10x levels of methylation seen in the seizure-associated locus in GNB1 for BOCA-FR or separately in the methylation fluctuations seen in HFM1 gene for paediatric brain cancer patients." (PMID 41345172, 2025).
female infertility (1 paper, 2024). Diminished or absent ability of a female to achieve conception. "HFM1 encodes a helicase for meiosis I that is essential for chromosome pairing, completion of synapsis, and recombination, and its knockout leads to male and female infertility." (PMID 39545410, 2024).
glaucoma (1 paper, 2022). Increased pressure in the eyeball due to obstruction of the outflow of aqueous humor. "Twelve of these genes, including PTPRB, HFM1, TAF1B, AAK1, FOXD1, EHMT1, and DNTT, are associated with glaucoma topical treatments (P < 1 × 10−5)." (PMID 36450729, 2022).
prostate carcinoma (1 paper, 2023). A carcinoma that arises from epithelial cells of the prostate gland. "The prognostic value of HFM1 and NEIL1 were previously reported in rectal and prostate cancers, but their effect on immune cell infiltration remains unclear." (PMID 36708047, 2023).
cancer (5 papers, 2014 to 2025). A tumor composed of atypical neoplastic, often pleomorphic cells that invade other tissues. "The functional enrichment analysis of the DEGs based on comparing samples with high and low HFM1 expression indicated that HFM1 might affect various cancer progression‐related pathways, such as the calcium signaling pathway and the cAMP signaling pathway." (PMID 36708047, 2023). "Consistent with the literature, the results of the present study showed fusion of the FGFR2 gene with nine different partners, namely, TACC2, BICC1, BTBD16, WAC, HFM1, HOOK1, INPP5F, C10orf90, and WDR11, in five different types of cancer." (PMID 35342406, 2022).
tumor (5 papers, 2008 to 2025). "HFM1, helicase for meiosis 1, was reported to be altered in tumors relative to control samples, and seen to be a tumor-suppressor here." (PMID 41048341, 2025). "We performed differential expression analysis between high‐ and low‐expression groups of HFM1/NEIL1 in tumor samples with the median value as a cutoff in both datasets." (PMID 36708047, 2023). "Nine tumors were altered at the HFM1 locus, as were two of their non-tumor DNA counterparts." (PMID 18784837, 2008). "The expression levels of two DDR genes, HFM1 and NEIL1, were downregulated in ESCC tumor tissues and had an independent effect on the infiltration of mast cells." (PMID 36708047, 2023). "We observed that HFM1 and NEIL1 were downregulated in ESCC tumor tissues." (PMID 36708047, 2023).
HFM1 also shares sentences with these, for which no sentence is quoted: ovarian insufficiency (3 papers); breast carcinoma (1); colorectal cancer (1); cyst (1); encephalitis (1); gastric cancer (1); neurodegenerative disease (1); oligospermia (1); soft tissue sarcoma (1).